CES2 (carboxylesterase 2)
Description:
Involved in the detoxification of xenobiotics and in the activation of ester and amide prodrugs. Shows high catalytic efficiency for hydrolysis of cocaine, 4-methylumbelliferyl acetate, heroin and 6-monoacetylmorphine. Hydrolyzes aspirin, substrates with large alcohol group and small acyl group and endogenous lipids such as triacylglycerol. Converts monoacylglycerides to free fatty acids and glycerol. Hydrolyzes of 2-arachidonoylglycerol and prostaglandins.
Synonyms: CE-2; ICE; CES2A1; PCE-2
Tractability: Small molecule: a high-quality ligand is known; it belongs to a druggable protein family. Antibody: UniProt predicts a signal peptide or a membrane-spanning region. PROTAC: ubiquitination databases record sites on it; its protein half-life has been measured; a small molecule that binds it is known.
Target class: Enzyme; Hydrolase
Gene: Protein-coding gene on chromosome 16 (66,934,444 to 66,945,096, forward strand). Ensembl gene ENSG00000172831.
Subcellular location: Endoplasmic reticulum lumen
Subcellular location (Human Protein Atlas): Golgi apparatus; Cytosol; Endoplasmic reticulum
Pathways (Reactome):
Drug ADME: Aspirin ADME
Metabolism: Phase I - Functionalization of compounds
Gene Ontology:
Molecular function: carboxylesterase activity; methylumbelliferyl-acetate deacetylase activity; protein binding; carboxylic ester hydrolase activity; retinyl-palmitate esterase activity
Biological process: cocaine catabolic process; detoxification; morphine catabolic process; prostaglandin metabolic process; xenobiotic metabolic process; retinol metabolic process
Cellular component: endoplasmic reticulum; endoplasmic reticulum lumen
Genetic constraint (gnomAD): Loss-of-function variants: 42 observed, 54.21 expected, observed/expected ratio (o/e) 0.77, 90% interval 0.6 to 1. The upper end of that interval is the gene's LOEUF score, 1, which puts it in group 4 of 6, group 1 being the genes least tolerant of losing a copy. Missense variants: 649 observed, 744.06 expected, observed/expected ratio (o/e) 0.87, 90% interval 0.82 to 0.93. Synonymous variants: 274 observed, 296.52 expected, observed/expected ratio (o/e) 0.92, 90% interval 0.84 to 1.02.
Homologues: Orthologues: chimpanzee CES2 (89% identical), macaque CES2 (88% identical), dog CES2 (74% identical), mouse Ces2c (71% identical), mouse Ces2e (70% identical), rat Ces2b (70% identical), rat Ces2g (69% identical), mouse Ces2b (69% identical), rat Ces2e (69% identical), mouse Ces2g (69% identical), rat Ces2c (69% identical), rat LOC679368 (68% identical), and 61 more. Paralogues in human: CES1 (47% identical), CES3 (46% identical), CES5A (44% identical), CES4A (42% identical), NLGN2 (35% identical), ACHE (34% identical), NLGN1 (34% identical), NLGN3 (34% identical), BCHE (34% identical), NLGN4X (34% identical), NLGN4Y (33% identical), TG (30% identical), and 1 more.
Diseases named in the same sentence as CES2 in open-access papers:
CES2 is named in the same sentence as 53 diseases in open-access papers, as found by Europe PMC text mining. Sharing a sentence is not in itself a finding about the gene and the disease. The quoted sentences say what the papers report.
liver steatosis (10 papers, 2016 to 2025). "Recently, human and murine CES2/Ces2c have been discovered as triglyceride (TG) hydrolases implicated in the development of obesity and fatty liver disease." (PMID 33872605, 2021). "In mice, Ces2c knockdown causes liver steatosis, whereas overexpression of CES2/Ces2c reverses liver steatosis and improves glucose tolerance on high-fat diet (HFD)." (PMID 33872605, 2021). "Likewise, low hepatic Ces2c expression has been linked to the development of fatty liver disease in mice as well, which has been reversed either by increasing hepatic Ces2c expression levels or ectopic expression of human CES2." (PMID 37059417, 2023). "Dietary PJT root extract supplementation possibly exerts its effects on obesity through gene expression regulation of Cyp2b and Ces2 members, which have recently been reported to be involved in the prevention of obesity and fatty liver disease in mice." (PMID 40888131, 2025). "In contrast, hepatic CES2/Ces2 expressions are considered to prevent fatty liver disease by improving glucose tolerance and insulin sensitivity." (PMID 37339977, 2023). "Although recent advances demonstrated the relevance of carboxylesterases, mainly the CES1/Ces1 and CES2/Ces2 families, to metabolic diseases such as obesity and fatty liver disease, differences and similarities among carboxylesterases were elucidated." (PMID 37339977, 2023). "In mice, obesity reduced CES2, whereas adenoviral delivery of human CES2 reversed hepatic steatosis, improved glucose tolerance, and decreased inflammation." (PMID 28099843, 2017). "Mechanistically, CES2 promotes lipid oxidation to reverse hepatic steatosis and dissociates activation of ER stress, as well as the downstream effector proteins IKK and JNK, from inflammation, Akt activation, and glucose intolerance." (PMID 28099843, 2017). "Carboxylesterase 2 controls a lipid network dysregulated in human obesity to reverse hepatic steatosis, glucose intolerance, and decrease inflammation in high-fat fed mice." (PMID 28099843, 2017). "(2016b) reported that mouse CES2 is a TAG hydrolase that prevents hepatic steatosis and that CES2 protein levels are decreased in patients with NASH." (PMID 28099843, 2017). "In addition to hepatic CES2, intestinal mCes2c overexpression protected mice from excessive diet-induced weight gain and liver steatosis." (PMID 39496863, 2025). "Similarly, another study suggested that CES2 promotes lipid oxidation to reverse hepatic steatosis and glucose intolerance." (PMID 39496863, 2025). "Previous study reported that HNF4α could prevent liver steatosis by controlling hepatic carboxylesterase 2 expression and modulating lipolysis, lipogenesis, and endoplasmic reticulum in NAFLD." (PMID 33415161, 2020). "However, on HFD, Ces2cint mice were protected from diet‐induced obesity and liver steatosis, highlighting an important function of Ces2c in the small intestine during metabolic stress, as suggested for hepatic Ces2c/CES2." (PMID 30766961, 2019). "CES2 expression reversed high-fat feeding-induced hepatic steatosis." (PMID 28099843, 2017). "CES2 prevents liver steatosis by regulating lipolysis, ER stress and lipogenesis." (PMID 27075303, 2016). "However, these mice also show reduced WAT inflammation and hepatic steatosis and improved responses in the GTT and ITT assays compared with Ces2–/– mice." (PMID 39496863, 2025). "Thus, the specific restoration of liver CES2/Ces2 expression, but not CES1/Ces1, can be a potential strategy to overcome obesity and fatty liver disease." (PMID 37339977, 2023).
colorectal cancer (9 papers, 2014 to 2021). A primary or metastatic malignant neoplasm that affects the colon or rectum. "Immunohistochemical evaluation has shown moderate expression of CES2 in normal human colon tissue and a broad range of expression levels in colorectal cancer with downregulation in the course of cancer progression." (PMID 30867471, 2019). "Most of the colorectal cancer specimens analyzed in this study showed a considerable reduction in CES2 expression compared with adjacent normal tissue." (PMID 29651325, 2018). "Irinotecan (CPT-11) is an anticancer prodrug that is activated by the carboxylesterase CES2 and has been approved for the treatment of many types of solid tumors, including colorectal cancer." (PMID 29651325, 2018). "Most colorectal cancer specimens (70%; 26 of 37) showed lower CES2 mRNA levels (≥1.5-fold lower) than the adjacent normal tissue, and only 30% (12 of 37) showed similar (<1.5-fold lower) or higher CES2 mRNA levels." (PMID 29651325, 2018). "S100 calcium-binding protein A9, annexin A3, nicotinamide phosphoribosyltransferase, carboxylesterase 2 and calcium activated chloride channel A1 were probably potential biomarkers of colorectal cancer." (PMID 27661117, 2016). "Reduced transcript levels of the CES2 gene have been reported in colorectal cancer." (PMID 34178034, 2021). "Thus, CES2 expression in colorectal cancer could be a key determinant of the therapeutic efficacy of this drug." (PMID 29651325, 2018). "E4bp4 regulates Ces2 enzymes through inhibition of the repressor activity of REV-ERBα, thereby impacting the metabolism and pharmacokinetics of the Ces2 substrate CPT-11 (or irinotecan, a first-line drug for treating colorectal cancer)." (PMID 32226546, 2020). "CES2 expression differs in non-neoplastic tissues and varies between different tumor types including colorectal cancer (CRC), pancreatic ductal adenocarcinoma (PDAC), lung adenocarcinoma and breast cancer." (PMID 30867471, 2019).
Obesity (9 papers, 2017 to 2025). Accumulation of substantial excess body fat. "Because the prevalence of obesity is associated with a higher risk for the development of inflammatory bowel diseases, we further investigated CES2 mRNA expression levels in colon biopsies from patients suffering from ulcerative colitis and Crohn’s disease." (PMID 33872605, 2021). "Thus, decreased CES2 is a conserved feature of obesity and plays a causative role in the pathogenesis of obesity-related metabolic disturbances." (PMID 28099843, 2017). "Thus, decreased CES2 appears to be a causative factor in the progression of hepatic metabolic disease and suggests that strategies restoring CES2 activity may prove effective in the treatment of obesity-associated metabolic disease." (PMID 28099843, 2017). "In some ways, Ces2–/–A mice seem to display a form of “healthy” obesity, characterized by increased body weight and WAT and liver compartment size." (PMID 39496863, 2025). "Taken together, presented data imply a critical role for CES2/Ces2c in regulation of TG hydrolysis in the small intestine and, most importantly, link intestinal lipid homeostasis with obesity and inflammatory bowel disease." (PMID 35437952, 2022). "eIF2α phosphorylation was decreased by diet-induced obesity, and CES2 expression reversed this effect." (PMID 28099843, 2017). "Addition of human CES2 resulted in alterations of endogenous mouse isoforms, with profiles similar to those observed in obesity with lower Ces2a and Ces2c and higher Ces2e." (PMID 28099843, 2017). "In conclusion, CES2 is a robust and reproducible regulator of intermediary metabolism that is altered in mouse and human obesity." (PMID 28099843, 2017). "Lipidomic analysis identified a network of CES2-regulated lipids altered in human and mouse obesity." (PMID 28099843, 2017). "This work identifies dysregulated hepatic biochemical networks in human obesity and establishes CES2 as a regulator of metabolic disease." (PMID 28099843, 2017). "Although the majority of serine hydrolases were unaffected by obesity, the activities of CES2 and AADAC were significantly reduced." (PMID 28099843, 2017). "In addition, our findings identified the Cyp2b and Ces2 gene members as potential targets for the development of functional foods for obesity treatment." (PMID 40888131, 2025). "However, human and murine CES2/Ces2c can also act as potent TG and DG hydrolases involved in the development of obesity and fatty liver disease." (PMID 35437952, 2022). "To determine whether obesity alters CES2 function in mice, we determined the levels of Ces2 isoforms in genetic and diet-induced murine models of obesity." (PMID 28099843, 2017). "Overall, we identified lipids altered by obesity in humans and mice that are regulated by CES2." (PMID 28099843, 2017). "Sphingosine and C16:0 S1P were decreased by obesity and increased by CES2 expression." (PMID 28099843, 2017). "HNF4α has been reported to play a key role in controlling hepatic CES2 expression in diabetes, obesity, or NASH; thus, we also investigated and found that HNF1α positively regulates CES2 expression though much need to be done in the future (data not shown)." (PMID 31223625, 2019). "Together, this study elucidates intestinal Ces2c/CES2 as a target to counteract NAFLD and obesity development." (PMID 30766961, 2019). "We identified reduced hepatic activity of carboxylesterase 2 (CES2) and arylacetamide deacetylase (AADAC) in human obesity." (PMID 28099843, 2017). "Although diet-induced obesity produced the expected increase in PKCε translocation to the membrane, CES2 was without effect." (PMID 28099843, 2017).
colon carcinoma (5 papers, 2002 to 2023). "We also observed that agonistic agents for the Pregnane X receptor, a candidate for the transcription factor of CES2 in human hepatoma cells, did not stimulate CES2 expression in colon cancer cells." (PMID 32961616, 2020).
pancreatic cancer (4 papers, 2016 to 2025). "High intratumoral CES2 expression is desirable for therapeutic efficacy, a concept strongly supported by survival data in pancreatic cancer." (PMID 41438085, 2025). "This discovery makes CES2 a potential new target for the treatment of pancreatic cancer." (PMID 38020758, 2023). "The strong associations between the loss of MAP4K5 expression and loss of E-cadherin or reduced CES2 expression may suggest an important role of MAP4K5 in epithelial-to-mesenchymal transition, chemotherapy resistance and tumor progression in pancreatic cancer." (PMID 27023625, 2016). "The strong associations between low MAP4K5 expression and loss of E-cadherin, reduced CES2 expression and decreased overall survival may suggest an important role of MAP4K5 in epithelial-to-mesenchymal transition, chemotherapy resistance and tumor progression in pancreatic cancer." (PMID 27023625, 2016).
breast carcinoma (3 papers, 2014 to 2026). "An example is the use of CES2-mediated targeting potential, which is proposed as a prognostic biomarker for breast cancer because of the high CES2 expression levels in these cells." (PMID 41562770, 2026). "For example, it was recently reported that siRNA directed against hCE1 (PMPMEase), but not CES2, inhibited RhoA demethylation and altered the morphology of breast cancer cells." (PMID 25228915, 2014).
diabetes (3 papers, 2017 to 2019). "Our model that includes non-genetic factors such as age, diabetes and hypertension as well as genetic variants in VKORC1 (rs9923231), CYP2C9 (rs2860905 and 1856908), CES2 (rs4783745), and ABCB1 (rs10276036), explained 60% of the variability in warfarin dose requirements among Puerto Ricans." (PMID 28638342, 2017).
Insulin resistance (3 papers, 2017 to 2025). Increased resistance towards insulin, that is, diminished effectiveness of insulin in reducing blood glucose levels. "Additionally, glucose tolerance and insulin resistance parameters were markedly improved in Ces2–/-–V mice, especially females." (PMID 39496863, 2025). "Remarkably, CES2 dissociates activation of ER stress, IKK, and JNK from inflammation and insulin resistance." (PMID 28099843, 2017). "CES2 dramatically decreased hepatic levels of DAGs, which stimulate PKC enzyme activity to induce insulin resistance." (PMID 28099843, 2017). "Our study elucidates Ces2a and CES2 as microsomal DAG and lysoPC hydrolases in vivo and suggests that aberrant hepatic lipid signaling due to decreased hepatic CES2/Ces2a expression is an important driver in the development of obesity-induced NAFLD and insulin resistance in humans and mice." (PMID 37059417, 2023).
Glucose intolerance (2 papers, 2017 to 2023). Glucose intolerance (GI) can be defined as dysglycemia that comprises both prediabetes and diabetes. "Finally, we showed that HFD-induced hepatic DAG accumulation and glucose intolerance in Ces2a-ko mice can be reversed upon ectopic CES2 expression, suggesting that Ces2a is a functional ortholog of CES2 and that Ces2a-ko mice are a validated mouse model for preclinical studies." (PMID 37059417, 2023). "In the setting of CES2 overexpression, as in conditional XBP1 knockout mice fed a fructose diet, improving lipid homeostasis reverses glucose intolerance despite elevated ER stress." (PMID 28099843, 2017).
Hypercholesterolemia (2 papers, 2017 to 2025). An increased concentration of cholesterol in the blood. "On the other hand, Ces2–/– mice exhibited fatty liver, adipositis, hypercholesterolemia and diminished glucose tolerance and insulin sensitivity, but without body mass changes." (PMID 39496863, 2025). "CES2 expression increased plasma cholesterol levels in chow-fed animals, but normalized diet-induced hypercholesterolemia." (PMID 28099843, 2017).
inflammatory bowel disease (2 papers, 2021 to 2023). A spectrum of small and large bowel inflammatory diseases of unknown etiology. "Low CES2 expression linked to hepatic inflammation in humans prompted us to investigate CES2 expression levels in colon biopsies of patients affected by inflammatory bowel disease." (PMID 33872605, 2021). "The marked reduction in Ces2a, Ces2b, and Ces2c expression in the DSS-induced colitis mouse model further corroborates the assumption that CES2 is involved in the development and/or progression of inflammatory bowel disease." (PMID 33872605, 2021). "Finally, we demonstrate reduced CES2 expression in the colon of patients with inflammatory bowel disease and a similar decline in Ces2 expression in the colon of a murine colitis model." (PMID 33872605, 2021).
liver cancer (2 papers, 2021 to 2023). An epithelial or non-epithelial malignant neoplasm that arises from the liver. "Notably in the context of liver cancer, CES2 is associated with drug metabolism, and ABCA12 has been associated with hepatic lipid metabolism." (PMID 34359777, 2021). "m6A methylation regulates lipid accumulation in HepaRG and HepG2 liver cancer cells by affecting carboxylesterase 2 (CES2) expression in a YTHDC2-dependent manner." (PMID 36859310, 2023).
lung carcinoma (2 papers, 2017 to 2024). "As expected, the results of rescue assays revealed that CES2 knockdown reversed the synergistic effect of GDNT and MMF against lung cancer in vitro." (PMID 38419324, 2024). "GDNT potentiated the role of MMF in inhibiting tumor growth and expressions of CES2 and IMPDH1/2 in lung cancer in vivo." (PMID 38419324, 2024). "In lung cancer cells, the expression of CES2 was increased by GDNT with/without MMF but was not significantly affected in the presence of MMF alone." (PMID 38419324, 2024). "CES2 knockdown reversed the synergistic effect of GDNT and MMF against lung cancer in vitro." (PMID 38419324, 2024). "Human CES2 also has the ability to catalyse the hydrolysis of retinyl palmitate to retinol and retinoic acid has been found to induce the expression of TNF receptors, TRAIL and caspase-8 in lung cancer cells resulting in acceleration of TNFa-induced apoptosis." (PMID 29178829, 2017). "Of note, results of following cellular functional assays confirmed that CES2 knockdown enhanced cell proliferation, repressed cell apoptosis and suppressed cell cycle arrest in S phase, which reversed the synergistic effect of GDNT and MMF on lung cancer cells (p < 0.001)." (PMID 38419324, 2024).
non-alcoholic steatohepatitis (2 papers, 2016 to 2017). "In contrast, CES2 is repressed in db/db mice, high fat diet-fed mice and patients with non-alcoholic steatohepatitis." (PMID 27075303, 2016). "The anti-inflammatory effects of CES2 overexpression suggest that decreased CES2 may promote the progression from NAFLD to non-alcoholic steatohepatitis (NASH)." (PMID 28099843, 2017).